SLA2 (Src like adaptor 2)
Description:
Adapter protein, which negatively regulates T-cell receptor (TCR) signaling. Inhibits T-cell antigen-receptor induced activation of nuclear factor of activated T-cells. May act by linking signaling proteins such as ZAP70 with CBL, leading to a CBL dependent degradation of signaling proteins.
Synonyms: MARS; SLAP-2; C20orf156; SLAP2; FLJ21992
Tractability: Antibody: its Gene Ontology location is reachable by antibodies, with high confidence; UniProt places it where antibodies can reach, with medium confidence. PROTAC: ubiquitination databases record sites on it.
Gene: Protein-coding gene on chromosome 20 (36,612,318 to 36,646,205, reverse strand). Ensembl gene ENSG00000101082.
Subcellular location: Cytoplasm; Cell membrane (Isoform 1); Cytoplasmic vesicle; Cytoplasm (Isoform 2)
Subcellular location (Human Protein Atlas): Golgi apparatus; Nucleoplasm; Vesicles
Pathways (Reactome):
Immune System: Negative regulation of FLT3
Gene Ontology:
Molecular function: protein binding; signaling adaptor activity
Biological process: negative regulation of calcium-mediated signaling; negative regulation of T cell receptor signaling pathway; negative regulation of transcription by RNA polymerase II; T cell activation; antigen receptor-mediated signaling pathway; B cell mediated immunity; regulation of immune response
Cellular component: cytoplasm; cytosol; endosome membrane; plasma membrane; cytoplasmic vesicle; late endosome
Genetic constraint (gnomAD): Loss-of-function variants: 21 observed, 29.19 expected, observed/expected ratio (o/e) 0.72, 90% interval 0.51 to 1.04. The upper end of that interval is the gene's LOEUF score, 1.04, which puts it in group 4 of 6, group 1 being the genes least tolerant of losing a copy. Missense variants: 295 observed, 328.43 expected, observed/expected ratio (o/e) 0.9, 90% interval 0.82 to 0.99. Synonymous variants: 129 observed, 143.35 expected, observed/expected ratio (o/e) 0.9, 90% interval 0.78 to 1.04.
Homologues: Orthologues: chimpanzee SLA2 (99% identical), macaque SLA2 (97% identical), guinea pig SLA2 (83% identical), dog SLA2 (82% identical), pig SLA2 (81% identical), rabbit SLA2 (81% identical), mouse Sla2 (80% identical), rat Sla2 (79% identical), tropical clawed frog sla2 (48% identical), zebrafish sla2b (40% identical), zebrafish sla2a (39% identical), Caenorhabditis elegans nck-1 (20% identical), and 1 more. Paralogues in human: SLA (39% identical), GRAP2 (21% identical), GRAP (20% identical), DAPP1 (19% identical), GRB2 (18% identical), SH2D5 (18% identical), NCK2 (18% identical), NCK1 (15% identical), GRAPL (14% identical).
Diseases named in the same sentence as SLA2 in open-access papers:
SLA2 is named in the same sentence as 12 diseases in open-access papers, as found by Europe PMC text mining. Sharing a sentence is not in itself a finding about the gene and the disease. The quoted sentences say what the papers report.
autism (1 paper, 2021). Persistent deficits in social interaction and communication and interaction as well as a markedly restricted repertoire of activity and interest as well as repetitive patterns of behavior. "SLA-2 also participates in the immune response, and associations with MIA-associated autism have been published." (PMID 33834688, 2021).
influenza (1 paper, 2018). An acute viral infection of the respiratory tract, occurring in isolated cases, in epidemics, or in pandemics; it is caused by serologically different strains of viruses (influenzaviruses) designated A, B, and C, has a 3-day incubation period, and usually lasts for 3 to 10 days. "These preliminary studies identified three potential new subdominant influenza epitopes restricted to SLA-2*11:04; PSGPLKAEI (Matrix 1), MVTTTNPLI (Matrix 1) and MVMELVRMI (NP)." (PMID 29772011, 2018). "In order to predict whether responses to other influenza proteins are made, it was necessary to know the preferred peptide binding motifs for SLA-1*14:02 and SLA-2*11:04." (PMID 29772011, 2018).
measles (1 paper, 2024). A highly contagious viral infection caused by the measles virus. "KEGG pathway analysis demonstrated that these genes related to SLA2 were mainly enriched in signal pathways, such as hematopoietic cell lineage, cell adhesion molecules (CAMs), natural killer cell mediated cytotoxicity, measles, and chemokine signaling pathway." (PMID 37688682, 2024).
pancreatic ductal adenocarcinoma (1 paper, 2024). An infiltrating adenocarcinoma that arises from the epithelial cells of the pancreas. "Besides, genome-scale analysis to identify prognostic markers in patients with early stage pancreatic ductal adenocarcinoma after pancreaticoduodenectomy, found that SLA2 is one of the prognostic markers." (PMID 37688682, 2024).
cancer (5 papers, 2013 to 2024). A tumor composed of atypical neoplastic, often pleomorphic cells that invade other tissues. "In our study, we found that SLA2 was differentially expressed in various types of cancer and its corresponding normal tissues." (PMID 37688682, 2024). "For the 43 paired samples, SLA2 expression was also significantly higher in cancer tissues than in matched normal adjacent tissue samples." (PMID 37688682, 2024). "Using the data from TCGA, we found that SLA2 expression was significantly elevated in 19 of 33 cancer types, including kidney renal papillary cell carcinoma (KIRP), kidney renal clear cell carcinoma (KIRC), stomach adenocarcinoma (STAD), among others." (PMID 37688682, 2024). "Four genes showed significant methylation-expression association in all five individual cancer types, BST2, SLA2, GSTT1, and GSTM1." (PMID 23742247, 2013). "With 10 DEG each, 2 biological processes were modulated, cellular responses to external stimuli with genes coding for prostaglandin protein, histone cluster, and heat shock protein and disease with NAG20, NRG1, SLA2, CSNK1A1L (signalling by WNT in cancer)." (PMID 31797963, 2019). "Moreover, cytokine and immune checkpoint blockade therapy has become a therapeutic strategy for various types of cancer, but no study has investigated whether SLA2 overexpression affects the tumor immune microenvironment of HNSCC." (PMID 37688682, 2024).
tumor (4 papers, 2016 to 2025). "In addition, we found that SLA2 gene expression was associated with tumor stage, clinical grade, and age." (PMID 37688682, 2024). "The aim of this study was to investigate the diagnostic value of SLA2 gene in HNSCC and its effect on tumor immune invasion." (PMID 37688682, 2024). "Taken together, SLA2 expression level is closely related to immune cell infiltration, which can lead to good prognosis of tumor patients." (PMID 37688682, 2024). "When a tumor is strongly infiltrated by immune cells, the expression of SLA2 will increased, and strong infiltration by immune cells is associated with a more favourable prognosis." (PMID 37688682, 2024). "Relevant studies have reported that SLA2 expression mediates cell proliferation, colony formation and tumor formation by destroying receptors." (PMID 37688682, 2024). "In conclusion, our work demonstrated that when a tumor is strongly infiltrated by immune cells, the expression of SLA2 will increased, and strong infiltration by immune cells is associated with a more favourable prognosis." (PMID 37688682, 2024). "SLA2 messenger ribonucleic acid (mRNA) levels were increased in HNSCC tumor tissues compared with normal tissues." (PMID 37688682, 2024). "The role of SLA2 has been extensively investigated in the context of viral and neoplastic diseases." (PMID 40920789, 2025). "In conclusion, we can infer that SLA2 may be involved in tumor formation and development by further affecting cell proliferation through the cellular microenvironment." (PMID 37688682, 2024). "Altogether, these results suggest that SLA2 may exert an anti-oncogenic function by triggering anti-tumor immune responses in HNSCC tissues." (PMID 37688682, 2024). "In this study, we found that SLA2 expression levels were positively correlated with the infiltration levels of numerous immune cells, suggesting that SLA2 might promote the anti-tumor immune response in tumor tissues." (PMID 37688682, 2024). "SLA2 may affect tumor development by regulating tumor infiltrating cells in TME." (PMID 37688682, 2024). "In addition, SLA2 expression levels were significantly correlated with the expression levels of many immune molecules, which might recruit immune cell infiltration, thereby exerting an anti-tumor effect." (PMID 37688682, 2024).
infection (2 papers, 2010 to 2012). The state of being infected such as from the introduction of a foreign agent such as serum, vaccine, antigenic substance or organism. "The transcript abundance of B2M, MHC class I antigen 2 (SLA-2), SLA-3, TAP2, and chaperones (such as GRP78) was markedly increased after infection with N-PRRSV while the transcript abundance of SLA-B was significantly decreased." (PMID 20614006, 2010). "mRNA expression measured at various time points (1, 3, 12, 24, 36 and 48 hpi) by real-time RT-PCR showed that infection of PK-15 cells with CSFV at either a MOI of 0.1 or 1.0, resulted in down-regulation of seven immune response genes, namely SLA-2, TAP1, SLA-DR, Ii, CD40, CD80, CD86." (PMID 22925563, 2012).
SLA2 also shares sentences with these, for which no sentence is quoted: asthma (1 paper); diabetes (1); gastric cancer (1); head and neck squamous cell carcinoma (1); pancreatic cancer (1).